FGFR2 (fibroblast growth factor receptor 2)
Diseases named in the same sentence as FGFR2 in open-access papers (continued):
Sharing a sentence is not in itself a finding about the gene and the disease.
cholangiocarcinoma (226 papers, 2014 to 2026). A carcinoma that arises from the intrahepatic biliary tree (intrahepatic cholangiocarcinoma) or from the junction, or adjacent to the junction, of the right and left hepatic ducts (hilar cholangiocarcinoma). "Significant association between FGFR2 alteration and cholangiocarcinoma indicates the therapy pathway of FGFR." (PMID 41361128, 2025). "Dysregulated FGFR2 expression and signaling have been implicated in several malignancies, including gastric cancer, cholangiocarcinoma, and endometrial carcinoma." (PMID 41150770, 2025). "In cholangiocarcinoma, ultra-high-sensitivity digital PCR technology has achieved detection of FGFR2 secondary mutations at frequencies as low as 0.1%." (PMID 41514604, 2025). "A gain-of-function mutation in PIK3CA was linked to acquired resistance to FGFR2 inhibitors in a patient with intrahepatic cholangiocarcinoma, underscoring its role in disease progression and therapy resistance." (PMID 41300430, 2025). "In cholangiocarcinoma, FGFR2 fusions and truncation variants (e.g., FGFR2ΔE18) represent mechanistically distinct driver events." (PMID 41514604, 2025). "Multiple studies have shown that altered FGF signaling has a significant association with tumor progression in cholangiocarcinoma, especially FGFR2 fusions with a frequency of approximately 10–15% cases." (PMID 39796710, 2024). "Presently, derazantinib lacks approval for treating cholangiocarcinoma with FGFR2 mutation or amplification." (PMID 38730642, 2024). "The preliminary responses observed in patients with cholangiocarcinoma harboring FGFR2 fusions and/or mutations, HER2-negative breast cancer including TNBC, and CRPC form the basis for further investigations of tinengotinib." (PMID 38297981, 2024). "Churi et al19 found that FGFR genetic aberrations were associated with better prognosis in cholangiocarcinoma; they examined the mutation profile of cholangiocarcinoma and found that the median OS of FGFR2 rearrangement-positive patients was 38.8 months." (PMID 38986528, 2024). "The application of fibroblast growth factor receptor (FGFR)−2 selective tyrosine kinase inhibitors (TKIs) in cholangiocarcinoma (CCA) with FGFR2 fusions has been reported to lead to mutations in the kinase domain of FGFR2." (PMID 38346946, 2024). "These three oral agents are all FDA-approved as subsequent line treatment options in the treatment of advanced FGFR-2 mutated cholangiocarcinoma after disease progression." (PMID 38203714, 2023). "Already, precision oncology has become standard of care in multiple cancers including nonsmall cell lung cancer (NSCLC), BRAF V600E mutated melanoma, fibroblast growth factor receptor 2 (FGFR2) rearranged cholangiocarcinoma, and others." (PMID 37686079, 2023). "In patients suffering from cholangiocarcinoma, the occurrence of polyclonal (i.e., multiple) FGFR2 kinase domain mutations is frequently reported at progression on reversible FGFR inhibitors." (PMID 37377403, 2023). "FGFRi are used in the treatment of advanced urothelial cancers with certain FGFR mutations, and previously treated advanced cholangiocarcinomas with FGFR2 gene alterations." (PMID 37589912, 2023). "It is also a proven therapeutic target; the FDA has approved the use of pemigatinib, infigratinib and futibatinib for cholangiocarcinoma with FGFR2 fusions and erdafatinib for bladder cancer with FGFR2/3 fusions and FGFR3 mutations." (PMID 37980453, 2023). "Given high diversity of FGFR2 gene alterations in cholangiocarcinoma, NGS can be regarded as an optimal diagnostic approach." (PMID 37891989, 2023). "Of note, FGFR2 alterations causing deletion of the extracellular domain were reported recently in cholangiocarcinoma." (PMID 37606995, 2023). "An additional FGFR1-3 inhibitor, infigratinib, has also shown early activity in the treatment of FGFR2-mutated advanced cholangiocarcinoma." (PMID 38203714, 2023).
cholangiocarcinoma (continued). "Genetic alterations detected in cholangiocarcinomas include fusions and mutations in FGFR2, mutations in IDH1 and KRAS, the BRAF V600E mutation, and ERBB2 amplification." (PMID 37108676, 2023). "Some alterations are more frequently observed in certain cancers, for example, FGFR3 mutations or translocations in bladder cancer, FGFR2 fusions or rearrangements in cholangiocarcinoma, and FGFR1 rearrangements in myeloid/lymphoid neoplasms." (PMID 37000035, 2023). "Tyrosine kinase inhibitors targeting FGFR have shown activity and tolerability in patients with FGFR2-mutated cholangiocarcinoma." (PMID 38203714, 2023). "Here, we report a case of calciphylaxis cutis in association with FGFR inhibitor therapy in a patient with FGFR2 rearranged cholangiocarcinoma." (PMID 35223258, 2022). "In 2020, FGFR-targeting erdafitinib and pemigatinib were approved by the Food and Drug Administration for use in FGFR3-mutated urothelial carcinomas and FGFR2-fusion cholangiocarcinomas." (PMID 36292044, 2022). "It has become clear that abrogating aberrant FGFR signalling in urothelial cancer (driven by FGFR3 mutations) and cholangiocarcinoma (driven by FGFR2 fusions) has led to improved clinical outcomes in these molecularly defined patient populations." (PMID 33268819, 2021). "Based on results of large clinical trials, targeted therapy drugs pemigatinib and ivosidenib have been approved by FDA to treat cholangiocarcinoma patients with FGFR2 fusions and IDH1 mutations, respectively." (PMID 34720757, 2021). "Unlike urothelial cancer, which has a high rate of FGFR3 mutations, cholangiocarcinoma harbours an increased frequency of fusions or rearrangements that favour FGFR2 and a diverse group of partner genes." (PMID 33268819, 2021). "In our cohort, the frequencies of IDH1 mutations and FGFR2 fusions detected by ctDNA profiling in cholangiocarcinoma were 7.4 and 4.8%, respectively." (PMID 34720757, 2021). "Also, in FGFR2-driven cholangiocarcinoma, mutations in PIK3CA and PTEN frequently occurred upon acquired resistance to FGFRis28." (PMID 41361008, 2026). "We report here on a patient with a cholangiocarcinoma bearing an FGFR2 mutation." (PMID 40338217, 2025). "Based on clinical experience in adult cancers, it has become clear that aberrant FGFR-mediated signaling is predictive of response to FGFR inhibitors in urothelial cancer (mainly driven by FGFR3 mutations) and cholangiocarcinoma (mainly driven by FGFR2 fusions)." (PMID 40510032, 2025). "Lirafugratinib is a highly FGFR2-selective inhibitor engineered to spare other FGFR paralogs and retain potency against prevalent resistance mutations, with early clinical responses in FGFR2-altered cholangiocarcinoma, including in patients previously exposed to FGFR inhibitors." (PMID 41032264, 2025). "Intriguingly, lirafugratinib was also able to suppress signalling and tumour growth induced by common FGFR2 kinase domain mutations associated with acquired resistance to pan-FGFR inhibitor treatment in cholangiocarcinoma patients such as the FGFR2V564F gatekeeper mutation." (PMID 38791079, 2024). "However, mosaic FGFR2 alterations have been linked to a number of neoplasms including colon, breast, gastric, endometrial, esophageal and cholangiocarcinoma." (PMID 38265560, 2024). "While cholangiocarcinomas harboring these actionable mutations are less prevalent than FGFR2 rearrangements, they seem to represent an additional population that may benefit from FGFR inhibition." (PMID 38710951, 2024). "It is evident that FGFR2 fusion mutations are relatively highly enriched in cholangiocarcinoma." (PMID 36612035, 2022). "In addition, 24 patients with FGFR2 fusion mutations were reported in the MSKCC 10,000 sequencing data, including 18 cases of cholangiocarcinoma (242 cases in total), accounting for 75% of all FGFR2 fusion mutations." (PMID 36612035, 2022).
cholangiocarcinoma (continued). "Furthermore, a phase III study (FIGHT-302) is currently ongoing to test the efficacy of Pemigatinib as a first-line treatment versus chemotherapy in patients with advanced cholangiocarcinoma with FGFR2 mutations." (PMID 34768421, 2021). "In addition, these studies have also identified new, recurrent driver genetic alternations in cholangiocarcinoma, such as FGFR2 fusion and IDH1 mutations that are potentially actionable with available pan-FGFR inhibitors and IDH1 inhibitors." (PMID 33451059, 2021). "However, IDH1-mutations are detected in only 13-15% of patients with cholangiocarcinoma and FGFR-2 fusion in only about 13-15% of patients with iCCA." (PMID 34858809, 2021). "Furthermore, cholangiocarcinoma harboring FGFR2 translocation and concomitant KRAS mutation are only rarely reported." (PMID 27102149, 2016). "Infigratinib demonstrated a consistent efficacy of 37.9% ORR; however, owing to insufficient statistical power, definitive conclusions could not be drawn, highlighting the limitations of conducting clinical trials on the ultra-rare disease of FGFR2 mutation-positive cholangiocarcinoma." (PMID 41008893, 2025). "Notably, several next-generation FGFR inhibitors have shown preclinical activity and preliminary clinical activity in patients with cholangiocarcinoma harboring FGFR2 kinase domain mutations and urothelial cancer harboring FGFR3 kinase domain mutations following previous FGFR inhibitor treatment." (PMID 38710951, 2024). "Pemigatinib achieved an ORR of 35.5% and extended median overall survival (OS) to 21.7 months in cholangiocarcinoma patients with FGFR2 fusions." (PMID 41584352, 2026). "Infigratinib is a selective oral FGFR1–3 inhibitor designed for FGFR-altered cancers, particularly FGFR2 fusion-positive cholangiocarcinoma." (PMID 41041285, 2025). "For example, the pivotal FIGHT-202 trial (NCT02924376) reported partial responses in a small subset of cholangiocarcinoma patients harboring non-FGFR2 alterations (e.g., other FGF/FGFR pathway abnormalities) or even no detectable FGF/FGFR alterations." (PMID 41430037, 2025). "By contrast, evidence from FGFR2-fusion intrahepatic cholangiocarcinoma is limited and sometimes inconsistent, underscoring the need for tumor-specific interpretation of FGFR–interferon crosstalk." (PMID 41514604, 2025). "The FIGHT-202 trial (Phase II, multicenter, open-label) demonstrated the antitumor efficacy of pemigatinib in previously treated patients with FGFR2 fusion or rearrangement–positive cholangiocarcinoma." (PMID 41514604, 2025). "In patients with FGFR2 fusion–positive cholangiocarcinoma, approximately 60% develop one or more secondary FGFR2 kinase domain alterations upon progression, most frequently at N550 and V565." (PMID 41514604, 2025). "Infigratinib is a selective FGFR1–3 inhibitor developed for FGFR2 fusion-positive cholangiocarcinoma." (PMID 41041285, 2025). "Biparatopic antibodies show superior inhibition of growth and transformation of FGFR2 fusion driven cholangiocarcinoma cell lines." (PMID 40014401, 2025). "FGFR2 fusion- or rearrangement-positive cholangiocarcinoma patients treated with futibatinib, a covalent FGFR inhibitor, also experience clinical benefit." (PMID 40558236, 2025). "The FIGHT-202 study led to the approval of pemigatinib in cholangiocarcinoma based on its efficacy in patients with FGFR2 fusions and rearrangements (N = 146; fusions/rearrangements, n = 107)." (PMID 40515475, 2025). "Pemigatinib, a selective FGFR1-3 inhibitor, is approved by the FDA for the treatment of advanced cholangiocarcinoma with FGFR2 fusions or rearrangements." (PMID 41430037, 2025). "Pemigatinib and futibatinib are approved for advanced cholangiocarcinoma with FGFR2 fusions, while erdafitinib is approved for metastatic urothelial carcinoma with FGFR2 or FGFR3 alterations." (PMID 41373672, 2025). "Sensitivity to FGFR1-3 inhibitors such as pemigatinib has been reported in patients with FGFR2 p.C382R mutant cholangiocarcinoma." (PMID 40906279, 2025).
cholangiocarcinoma (continued). "FGFR2 fusions occur in approximately 10–16% of cholangiocarcinomas, with common fusion partners including BICC1, AHCYL1, and PPHLN1." (PMID 41514604, 2025). "Futibatinib, a potent irreversible pan-FGFR1-4 inhibitor, demonstrated durable activity in the FOENIX-CCA2 study, with an ORR of 41.7%, leading to FDA approval for FGFR2-fusion-positive cholangiocarcinoma." (PMID 41153346, 2025). "In cholangiocarcinoma research, CNN-based models have revealed multiple copy number and structural variation features associated with FGFR2 resistance." (PMID 41514604, 2025). "Prospective investigations of FGFR2 fusion-positive cholangiocarcinoma have established standardized protocols: baseline detection followed by initial assessment at 4 weeks of treatment, with subsequent monitoring every 8 weeks." (PMID 41514604, 2025). "A recent genomic profiling analysis of cholangiocarcinoma harboring FGFR2 fusions or rearrangements showed that co-occurring CDKN2A/B alterations were associated with significantly shortened progression-free survival." (PMID 40013221, 2025). "We identify biparatopic FGFR2 antibodies that are effective against FGFR2 fusion driven cholangiocarcinoma." (PMID 40014401, 2025). "In FGFR2-altered cholangiocarcinoma, clinical sequencing at progression frequently reveals polyclonal secondary FGFR2 mutations and pathway rewiring, limiting the durability of FGFR inhibitors." (PMID 41275311, 2025). "Pemigatinib, infigratinib, and futibatinib have been approved by the US Food and Drug Administration (FDA) for the treatment of patients with previously treated advanced cholangiocarcinoma with FGFR2 fusion or rearrangement." (PMID 40338217, 2025). "In conjunction with FGFR2 fusions, Isocitrate dehydrogenase 1 (IDH1) mutations, the BRAF p.V600E hotspot, and others are found in approximately 30–40% of patients with cholangiocarcinoma, particularly intrahepatic subtypes." (PMID 41153346, 2025). "We chose Infigratinib, a selective FGFR1-3 inhibitor to target FGFR signaling (FDA-approved for treatment of cholangiocarcinoma with an FGFR2 fusion), and Everolimus which inhibits the formation of the mTOR complex, for testing in combination with BCL2i." (PMID 40568132, 2025). "Actually, three small molecular inhibitors of FGFR2 including futibatinib, pemigatinib, and tasurgratinib have been approved as of 2024 and are clinically used against cholangiocarcinoma with FGFR2 fusion genes in Japan." (PMID 41226813, 2025). "In cholangiocarcinoma, patients harboring identical FGFR2 fusions frequently exhibit marked heterogeneity in molecular profiles and downstream signaling cascades." (PMID 41514604, 2025). "Translocations involving FGFR2 gene fusions are common in cholangiocarcinoma and predict response to FGFR kinase inhibitors." (PMID 40014401, 2025). "In addition, polyclonal point mutations in the kinase domain of FGFR2 were shown to induce drug resistance in human cholangiocarcinoma (CCA) patients." (PMID 40724880, 2025). "Selective TKIs are approved for cholangiocarcinoma (CCA) with FGFR2 fusions; however, their application is limited by a characteristic pattern of adverse events or evocation of kinase domain mutations." (PMID 38346946, 2024). "Futibatinib and pemigatinib have received approval for the treatment of cholangiocarcinoma patients with FGFR2 fusions or rearrangements." (PMID 39421453, 2024). "There have been recent developments and approvals of therapies targeting fusion oncogenes, such as those for cholangiocarcinomas with FGFR2 fusions and solid tumors with NTRK fusions in the area." (PMID 38363490, 2024). "Pemigatinib, evaluated in the FIGHT-202 trial, exhibited a 36% overall response rate in patients with cholangiocarcinoma harboring FGFR2 fusions or rearrangements." (PMID 39421453, 2024).
cholangiocarcinoma (continued). "As with the Next-Generation Sequencing (NGS) assay, the latest National Comprehensive Cancer Network (NCCN) guidelines recommend it as a test for FGFR2 fusion/other FGFR aberrations in cholangiocarcinoma." (PMID 38831455, 2024). "NCCN guidelines also recognize that the use of cell free DNA (cfDNA) testing can detect some FGFR2 fusion breakpoints in cholangiocarcinoma, but the sensitivity is lower than that of tumor tissue testing." (PMID 38831455, 2024). "In line with this, postzygotic somatic activating FGFR2 alterations were found in various cancer types including colon, breast, gastric, endometrial, esophageal and cholangiocarcinoma." (PMID 38265560, 2024). "The FIGHT 202 trial led to FDA and EMA approval for the use of pemigatinib in pretreated advanced cholangiocarcinoma with FGFR2 fusion/rearrangements." (PMID 38895132, 2024). "We examined a prevalence of FGFR2 genetic alterations and their clinicopathological significance in combined hepatocellular–cholangiocarcinoma (cHCC-CCA)." (PMID 38532197, 2024). "In cholangiocarcinoma, pathways like FGFR2, HER2, EGFR, VEGF, and several other signaling pathways have been targeted due to their frequent dysregulation in this cancer type." (PMID 38730642, 2024). "Based on the advantages of NGS testing and past practical experience, the latest NCCN and ESMO guidelines recommend it as a detection method for FGFR2 fusion/other FGFR aberrations in cholangiocarcinoma." (PMID 38831455, 2024). "For example, erdafitinib is approved for treating locally advanced or metastatic urothelial cancer patients with FGFR2/FGFR3 mutations, and pemigatinib is approved for treating cholangiocarcinoma with FGFR2 fusion/rearrangement." (PMID 39583123, 2024). "suggests that oncogenic Fibroblast Growth Factor Receptor 2(FGFR2) signaling drives NF-κB-dependent glycolysis in intrahepatic cholangiocarcinoma and that metabolic reprogramming in response to FGFR inhibition confers new targetable vulnerabilities." (PMID 39759516, 2024). "Molecular targets such as FGFR2 fusion, IDH1/2 mutation, and HER2 amplification are currently being evaluated for targeted treatment approaches in cholangiocarcinoma (CCA), with most of these strategies still in the clinical investigation phase." (PMID 39199633, 2024). "Prospective biomarker data were available for one patient with a PR who had cholangiocarcinoma harboring an FGFR2 fusion." (PMID 38297981, 2024). "Recently, pemigatinib, an FGFR2 inhibitor used in patients with FGFR2-rearranged cholangiocarcinoma, received FDA approval for relapsed/refractory myeloid and/or lymphoid neoplasms with FGFR1 rearrangements." (PMID 38337573, 2024). "Gene fusions between FGFR2 and various genes are commonly identified in cholangiocarcinoma (CCA), playing a crucial role in tumorigenesis and tumor progression." (PMID 38831455, 2024). "These FGFR2 fusions play the most critical role in cholangiocarcinoma as they lead to constitutively active FGFR2 to subsequently promote tumor growth and survival." (PMID 39796710, 2024). "Especially, enhanced PI3K/AKT pathway activation was more commonly observed in FGFR2 mutant cells, suggesting FGFR2 as a potential therapeutic target for cholangiocarcinoma." (PMID 38702814, 2024). "This case supports sequential FGFR-targeting therapies for FGFR2 fusion–positive cholangiocarcinoma, with futibatinib acting as rescue therapy after failure of ATP-competitive inhibitors." (PMID 38895132, 2024). "The FDA has granted approval for Infigratinib, Pemigatinib, and Futibatinib in the treatment of cholangiocarcinoma with FGFR2 fusion, as well as Erdafitinib in the treatment of bladder cancer with FGFR3 mutation." (PMID 38831455, 2024). "Based on baseline tissue NGS analysis alone, patterns seen in patients with FGFR2 fusion-positive cholangiocarcinoma in FIGHT-202 were recapitulated here across multiple histologies harboring a variety of FGFR1–FGFR3 fusions and mutations." (PMID 38710951, 2024).